RAN (RAN, member RAS oncogene family)
Diseases named in the same sentence as RAN in open-access papers (continued):
Sharing a sentence is not in itself a finding about the gene and the disease.
Wilms tumor (1 paper, 2020). An embryonal neoplasm characterized by the presence of epithelial, mesenchymal, and blastema components. "In conclusion, our data provide evidence that RAN gene rs7132224 A>G polymorphism is significantly associated with increased Wilms tumor susceptibility." (PMID 31949483, 2020). "Results shown that RAN rs7132224 AG/GG genotypes significantly increased Wilms tumor risk when compared to AA genotype (adjusted OR=1.40, 95% CI=1.01-1.95, P=0.047)." (PMID 31949483, 2020). "The RAN rs56109543 CT/TT genotypes (adjusted OR=1.98, 95% CI=1.15-3.38, P=0.013) and RAN rs7132224 AG/GG genotypes (adjusted OR=2.80, 95% CI=1.64-4.77, P=0.0002) increased the risk of Wilms tumor among the children aged ≤18 months." (PMID 31949483, 2020). "Although our study is the first investigation about the association of RAN/RANBP2 gene SNPs with Wilms tumor risk, several flaws should be noted." (PMID 31949483, 2020). "Compared to RAN rs7132224 AA genotype, AG/GG genotypes were found significantly correlated with the risk of Wilms tumor." (PMID 31949483, 2020). "More comprehensive researches with lager sample size were warranted to validate the association between RAN/RANBP2 gene polymorphisms and Wilms tumor risk." (PMID 31949483, 2020). "Our results indicated that RAN and RANBP2 polymorphisms were associated with Wilms tumor susceptibility in Chinese children." (PMID 31949483, 2020). "In this study, three potentially functional polymorphisms (rs56109543 C>T, rs7132224 A>G, and rs14035 C>T) in the RAN and one (rs2462788 C>T) in the RANBP2 were chosen to investigate their association with Wilms tumor susceptibility." (PMID 31949483, 2020). "As far as we know, the current study is the first investigation regarding the association of RAN and RANBP2 gene polymorphisms with Wilms tumor susceptibility." (PMID 31949483, 2020). "Nevertheless, the effects of the RAN and RANBP2 gene polymorphisms on the tumorigenesis of Wilms tumor remain unclarified." (PMID 31949483, 2020). "Thus, we conducted this study to examine the association of RAN and RANBP2 gene polymorphisms with Wilms tumor risk as well as cumulative effects of polymorphisms in the two genes." (PMID 31949483, 2020). "Moreover, stratified analysis indicated that RAN rs56109543 CT/TT genotypes, RAN rs7132224 AG/GG genotypes and RANBP2 rs2462788 CT/TT genotypes remarkably increased Wilms tumor susceptibility among the subgroups." (PMID 31949483, 2020).
cancer (55 papers, 2011 to 2025). A tumor composed of atypical neoplastic, often pleomorphic cells that invade other tissues. "Several meta-analysis reports addressed the contribution of the RAN*rs14035 variant to cancer development among various ethnic populations." (PMID 37373948, 2023). "Our results were consistent with a comprehensive meta-analysis that confirmed the contribution of RAN*rs14035 to cancer risk." (PMID 37373948, 2023). "In the pan-cancer study, average mutation rates ranged from 0.23% for the RAN gene to 1.87% for the DICER1 gene." (PMID 36672288, 2023). "Egger’s regression test revealed publication bias in the association between RAN*rs14035 and cancer susceptibility (p = 0.046)." (PMID 36672288, 2023). "The XPO5*rs34324334 and RAN*rs14035 variants approached Hardy–Weinberg equilibrium among cancer-free controls (p-value > 0.05)." (PMID 37373948, 2023). "The RANBP2-mediated RAN GTPase regulation has been implicated in the initiation and progression of several cancers." (PMID 33816306, 2021). "Studies have shown that abnormal expression of RAN and subsequent genetic instability are associated with cancer progression." (PMID 32398961, 2020). "Formerly, several studies have been conducted to assess the association between XPO5 and RAN SNPs and cancer susceptibility in diverse populations." (PMID 32127945, 2020). "On the basis of the Bayesian hierarchical meta-analysis, XPO5 rs11077 and RAN rs3803012 SNPs were significantly associated with the risk of cancer." (PMID 32127945, 2020). "First, the association of RAN SNPs with overall cancer risk was evaluated by calculating pooled ORs, and both the rs14035 and rs3803012 polymorphisms were found to be associated with cancer risk." (PMID 32015773, 2020). "A Bayesian hierarchical meta-analysis was carried out to review and analyze the effect of XPO5 and RAN polymorphisms on cancer risk." (PMID 32127945, 2020). "Meanwhile, a meta-analysis was conducted based on available data, aiming at clarifying the association between RAN SNPs and cancer susceptibility." (PMID 32015773, 2020). "Since the Bayesian hierarchical meta-analysis is much more sensitive and confers more precise estimation compared with classical meta-analysis, it is powerful suggested that rs11077 SNP of XPO5 and rs3803012 SNP of RAN are associated with cancer risk." (PMID 32127945, 2020). "Several studies have inspected the association between XPO5 or RAN polymorphisms and the risk of various cancers, but the findings remain controversial." (PMID 32127945, 2020). "Thirdly, studies of XPO5 and RAN SNPs in the cancer predisposition field continue to emerge, which resulted in limited number of the relevant investigations." (PMID 32127945, 2020). "To substantiate the associations between the identified SNPs (XPO5 rs11077 and RAN rs3803012 SNPs) and cancer risk, we performed the eQTL analysis to assess the associations between SNPs and corresponding mRNA expression levels." (PMID 32127945, 2020). "In the present study, a total of five SNPs in XPO5 and RAN genes were comprehensively reviewed and analyzed to estimate their associations with the risk of overall cancer by Bayesian hierarchical meta-analysis." (PMID 32127945, 2020). "In this study, a systematic review was conducted for the association of all published SNPs in the RAN gene with the risk of overall cancer." (PMID 32015773, 2020). "Our classical meta-analysis (the results of this analysis were not included in this study) also demonstrated a significant increased association risk of RAN gene rs3803012 SNP in cancer." (PMID 32127945, 2020). "In the present study, we performed a systematic review for the association of RAN SNPs with overall cancer risk." (PMID 32015773, 2020). "It is an emerging field concerning the association of RAN SNPs with cancer risk, and further investigations are request for an updated meta-analysis." (PMID 32015773, 2020).
cancer (continued). "RAN GTPase and proteins involved in nuclear transport have been implicated in cancer progression, drug resistance, and cancer therapeutic development." (PMID 30671385, 2018). "Previous studies have shown that microRNA machinery genes—such as DICER, DROSHA, XPO5, and RAN—are associated with cancer development." (PMID 27611467, 2016). "Studies also proposed that the RAN rs3803012*G allele might affect miRNA-199a-3p targeting and decrease RAN mRNA expression in cancer cells, which may affect miRNA biosynthesis." (PMID 36672288, 2023). "The RAN*rs14035 variant showed a significant association with elevated risk of HCC compared to cancer-free controls among different hereditary models, including homozygote (OR = 2.44, 95% CI = 1.27–4.68, p-value < 0.001) and recessive (OR = 3.27, 95% CI = 1.83–5.83, p-value < 0.001)." (PMID 37373948, 2023). "Additionally, we performed various bioinformatic analyses regarding the XPO5 and RAN genes to focus light on the importance of these potential variants in the progression of carcinomas." (PMID 37373948, 2023). "Overall, RAN rs3803012 SNP might also become useful biomarkers for predicting cancer risk in general or specific population." (PMID 32015773, 2020). "In contrast, our Bayesian hierarchical meta-analysis which included 6,514 cases and 8,707 healthy subjects for the RAN gene rs3803012 SNP from 7 studies, demonstrated a significant association between rs3803012 SNP (homozygote or recessive model) and overall cancer risk." (PMID 32127945, 2020). "In addition, the minor GG genotype allele of the RAN gene rs3803012 SNP significantly increased the cancer risk (Log OR = 0.707, 95% CrI = 0.059, 1.385)." (PMID 32127945, 2020). "In summary, we systematically reviewed the association of RAN SNPs with the risk of overall cancer." (PMID 32015773, 2020). "In view of all this, Bayesian hierarchical meta-analysis suggests a potential role of the miRNA biogenesis genes XPO5 (rs11077 A/C) and RAN (rs3803012 A/G) SNPs in cancer risk, supplying novel clues to identifying new biomarkers with cancer-forewarning function." (PMID 32127945, 2020). "Therefore, in the present study, we carried out a Bayesian hierarchical meta-analysis including newly published articles to find a vivid and precise association between SNPs in XPO5 and RAN genes with cancer risk based on all available eligible studies." (PMID 32127945, 2020). "Currently, accumulating studies have explored the association between RAN SNPs and cancer risk." (PMID 32015773, 2020). "RAN/RANBP2 genes are reported to be associated with cancer development." (PMID 29706609, 2018). "Apart from TARBP2 and RAN, our trial sequential analysis results showed that the cumulative evidence for miRNA gene machinery variants was inadequate, and additional primary allelic discrimination studies for the other nine genes are warranted to validate the outcomes in various types of cancers." (PMID 36672288, 2023). "Hence, it could be inferred that RAN rs3803012 G allele might influence the targeting of hsa-miR-199a-3p and lead to reduced expression of RAN mRNA in cancer cells, further affecting a variety of miRNA biological synthesis." (PMID 32015773, 2020). "Therefore, RAN rs3809142 and rs7301722 could also have the potential to be functional SNPs as well as biomarkers for cancer risk prediction." (PMID 32015773, 2020). "Therefore, whether the polymorphisms in the RAN gene are cancer-related and how they affect the susceptibility to human cancer remain unclear." (PMID 32015773, 2020). "Over time, RANBP1 has been demonstrated to be variously involved in human cancers both for the role in controlling nuclear transport and RAN activity and for its ability to determine the efficiency of the mitotic process." (PMID 36672435, 2023).
cancer (continued). "RAN is a protein regulating the rate of nucleocytoplasmic shuttling, and cancer possessing KRAS activating mutation, c-Met enhancement, and PTEN-deletion are more sensitive to apoptosis induced by silencing RAN." (PMID 36834736, 2023). "Ras-related nuclear protein (RAN) which is overexpressed in various cancers, has been identified as a direct target of miR-197-3p." (PMID 36765536, 2023). "Pooling the data from 45 articles, our results reveal the association of DROSHA (A > G; rs10719), DGCR8 (G > A; rs417309), RAN (A > G; rs3803012), and GEMIN3 (C > A; rs197414) with a 19–93% higher susceptibility to overall cancer." (PMID 36672288, 2023). "The most prevalent genotype (T/T genotype) for the RAN*rs14035 variant in HCC patients was 45.8%, compared to 21.3% in cancer-free controls." (PMID 37373948, 2023). "Other genes that are differentially expressed in Bhas 42 CTA by TPA treatment include RAN, MTHFD2, WT1, and AURORA-A, which are markers that cause cancer formation and malignant transformation in humans and laboratory animals." (PMID 35328637, 2022). "The top eight pathways selected for the EGFR mutation samples include salivary secretion, RAN degradation, ECM‐receptor interaction, cancer miRNAs, measles, glycerophospholipid metabolism, MAPK pathway, and focal adhesion." (PMID 33682961, 2021). "Several researches illustrated that RAN-inhibitory peptide-loaded PEG-PLGA NPs have great potential in curbing cancer through limiting the formation of active forms of RAN 32-34." (PMID 31949483, 2020). "And RAN has been found to be highly expressed in a variety of cancers, and it has been demonstrated that overexpression of RAN can promote the invasive ability of cancer cells." (PMID 32398961, 2020). "RAN is overexpressed in many cancer cell lines, including the stomach, colon, pancreas, lung, and ovarian cancer." (PMID 32015773, 2020). "Studies have revealed that the up-regulation of RAN expression in various malignancies supports its role in cancer development 67-69." (PMID 32127945, 2020). "XPO5/RAN-GTP complex mediates the nuclear transport of pre-miRNAs in the miRNA processing system, its altered expression is indicated to be correlated with cancer risk." (PMID 32127945, 2020). "The RASSF1A/RAN/XPO6/nuclear actin pathway is aberrant in cancer cells where RASSF1A expression is lost and correlates with reduced MRTF‐A/SRF activity leading to cell adhesion defects." (PMID 31414556, 2019). "In this study, a meta-analysis was conducted to evaluate the association between SNPs in five genes (DROSHA, DGCR8, XPO5, RAN, and DICER1) involved in the canonical microRNA biogenesis pathway and human cancer risk." (PMID 27957388, 2016). "To determine if any of the partners of RAN are implicated in the biology of EOC, we performed an IHC analysis using a TMA containing a total of 286 cores of cancer specimens representing 143 patients." (PMID 24625450, 2014). "Several dynamically regulated Ras-related proteins were identified in this study, including RAB7A and RAN, which were increasingly overexpressed at the whole cell level with increased cancer progression." (PMID 24086712, 2013). "Kyoto Encyclopedia of Genes and Genomes pathway analysis showed that the 165 overlapping genes were enriched in cancer-related pathways, suggesting that RAN may promote NPC development by its RNA binding ability." (PMID 39510185, 2024). "RAN translocate HIF1α into the cytoplasm, contributing to cancer progression in mitochondria." (PMID 38666828, 2024). "RAN has also been considered a potential therapeutic target in certain cancers." (PMID 38666828, 2024).
cancer (continued). "Nucleotide sequence change in RAN (A > G; rs3803012) leads to modification of the binding site of the transcription factor NANOG, which is associated with the differentiation of pluripotent stem cells and various types of cancer." (PMID 36672288, 2023). "As for the RAN gene rs14035 and rs3809142 polymorphisms, both types of meta-analysis did not support the significant association with cancer risk." (PMID 32127945, 2020). "Both RAN and RANBP2 are involved in mitosis and are associated with a variety of cancers." (PMID 31949483, 2020). "Analysis of associations between SNPs from DROSHA, DGCR8, XPO5, RAN, and DICER1 and cancer risk." (PMID 27957388, 2016). "However, despite the vital importance of RAN in cancer cells it has been difficult to determine which function of this protein is involved in tumorigenesis." (PMID 24625450, 2014). "Recent findings have shown that silencing RAN expression could induce more apoptosis in cancer cells, and therefore is a promising cancer therapeutic target." (PMID 24377043, 2013). "Therefore, the SNPs located in the 3′-UTR of RAN may affect its expression by altering mRNA stability and subsequently participate in cancer genesis and development." (PMID 32015773, 2020). "However, the results did not indicate a correlation between SNPs in XPO5 and RAN genes with cancer risk." (PMID 32127945, 2020). "However, given that nuclear transport is more active in cancer cells due to the high proliferation index, the activity of RAN and its functional partners may be more important for GBM survival." (PMID 30671385, 2018). "We analyzed the mRNA expression levels of miRNA machinery components (DROSHA, DGCR8, XPO5, RAN, DICER, TARBP2, and AGO2) utilizing mRNA-Seq data from The Cancer Genome Atlas (TCGA) and The Genotype-Tissue Expression (GTEx) projects." (PMID 39404265, 2024). "Downregulation of RAN post-NVA-IT treatment signifies the occurrence of cell cycle arrest and cell death in cancer cells." (PMID 37900279, 2023). "TPA-associated genes differentially expressed in the Bhas 42 CTA included markers such as RAN, MTHFD2, WT1, and AURORA-A, which lead to carcinoma formation and malignant transformation in humans and test animals." (PMID 35328637, 2022). "In our analysis, 6 out of 18 genes (EIF4A3, RAN, PSMA3, CCNA2, POLR2D, CDC27) were scored as SL hits against RB1 in at least two human cancer cell lines screens." (PMID 33591981, 2021). "The RAN protein is also a well-known downstream modulator of the PI3K signaling pathway, which mediates cancer cell invasion and metastasis." (PMID 26147304, 2015). "The pathways associated with the largest age-related decreases in miRNA levels of BMSCs (P ≤ 0.05) included those involved in molecular mechanisms of cancer, PTEN signaling, mTOR signaling, and RAN signaling." (PMID 22169120, 2011). "While selective inhibitors of XPO1 have already been approved for adjuvant therapy in other cancers, inhibitors for RAN and RPRD1B1 have not yet been developed." (PMID 38804617, 2024). "Furthermore, miR-197-3p directly regulates other genes implicated in trastuzumab resistance, including FOXJ2, MTHFD1, RAN, TUSC2, and FUS1, though their specific roles in drug resistance and cancer progression require further investigation." (PMID 38534787, 2024). "Evidence suggests that the genes XPO5 and RAN may contribute to the development of tumors, including HCC, and may be involved in the mechanism by which microRNAs (miRNAs) are synthesized in cancer." (PMID 37373948, 2023). "RAN and HNRNPA2B1 showed differential expression in most cancers." (PMID 35151325, 2022). "Moreover, RAN protein is also a well-known downstream modulator of the PI3K signaling pathway, which mediates cancer cell invasion and metastasis." (PMID 32015773, 2020).
cancer (continued). "We excluded 148 articles by reading titles and abstracts: 92 were functional studies; 29 were review, meta-analyses, or case reports; 18 were not related to RAN SNPs; 5 were not related to carcinoma; and 4 were focused on cancer prognosis." (PMID 32015773, 2020). "Given that most cancers, including GBM, demonstrate a hyper-dependency on nuclear transport, a selective inhibition of RAN/KPNB1 activity by importazole may represent an innovative and effective treatment for GBM." (PMID 30671385, 2018). "Finally, for DMRs whose associated genes had increased expression upon treatment with FQI1, we observed enrichment of GO terms for pathways in cancer (e.g. PIAS4, SMAD3, TRAF4, MAP2K1) and RNA transport (e.g. NUP188, EIF3A, NUP35, RAN) in both hyper and hypomethylated DMRs." (PMID 27845898, 2016). "Interestingly, RNA interference studies have shown that RAN down regulation drastically affects cancer cell survival but not that of normal cells." (PMID 24625450, 2014).